INS (insulin)
Diseases named in the same sentence as INS in open-access papers (continued):
Sharing a sentence is not in itself a finding about the gene and the disease.
Hypertension (continued). "High-quality studies should elucidate: insulin-RAAS crosstalk in hypertension pathogenesis and dynamic MAP fluctuations in PCOS." (PMID 41040863, 2025). "Our findings establish CMI as a significant predictor of cardiovascular events in the aging population, with the relationship partially mediated through hypertension and insulin resistance pathways." (PMID 40235661, 2025). "The use of insulin therapy was comparable between the sexes, as was the prevalence of hypertension and smoking." (PMID 40869604, 2025). "In the MLP model, the final features were body weight, uric acid, PLT, BMI, ALT, hypertension, fasting insulin, ALB, DM, LDL-C, AST, creatinine, height, age, HDL-C, HbA1c, total bilirubin, TG, TC, and sex." (PMID 40361915, 2025). "During the multiple linear regression analysis, UA and Galectin-3 plasma levels, age, the existence of hypertension, and treatment with insulin were again directly related to the decrease in eGFR during follow-up." (PMID 40806886, 2025). "When cells are resistant to insulin, this vasodilatory effect is diminished, contributing to increased vascular resistance and hypertension." (PMID 40093747, 2025). "Insulin affects hypertension by acting as a peripheral vasodilator through endothelial nitric oxide-dependent pathways and increasing sodium retention in the renal system." (PMID 39941702, 2025). "We compared our results with studies examining the relationship between insulin-based indices and hypertension." (PMID 40778272, 2025). "Among these, the estimated glucose disposal rate (eGDR), which incorporates waist circumference (WC), hypertension, and glycated hemoglobin (HbA1c), is used to assess individual insulin sensitivity." (PMID 41171818, 2025). "Oxidative stress is connected with organ injuries, such as left ventricular hypertrophy and carotid intima-media thickness, in children with hypertension, along with metabolic abnormalities, adipose tissue volume, and insulin resistance." (PMID 40019178, 2025). "Elevated blood glucose levels result in insulin accumulation and persistent proliferation of vascular smooth muscle, which in turn leads to vascular spasms, increased vascular resistance, hypertension, and ultimately the development of PE." (PMID 40980178, 2025). "Reviewing the patient’s history revealed unexplained weight loss of 16 kg over the past 7 years, with severe constipation, poor glycemic control despite insulin therapy, and hypertension under three medication treatments." (PMID 40823068, 2025). "The development of hypertension is attributed to the vasodilatory effects of insulin counteracted by the vasoconstrictive properties of FFA." (PMID 40310144, 2025). "The interaction between oxidative stress and impaired insulin metabolic signaling is likely central to the pathogenesis of hypertension, cardiometabolic syndrome (CMS), and CVD." (PMID 40336963, 2025). "Intergroup comparisons of baseline characteristics across clusters indicated that age, sex, DM duration, HbA1c, insulin use, hypertension, hyperlipidemia, and serum creatinine levels were approximately the same trend across the four clusters." (PMID 40251316, 2025). "MetS was defined as meeting at least three of the following five criteria: impaired insulin metabolism, reduced glucose tolerance, hypertension, dyslipidemia, and large waist circumference." (PMID 40313386, 2025). "As a result, insulin and insulin growth factor-1 (IGF-1) in the placenta stimulate fetal hyperinsulinemia, leading to macrosomia, increasing the risk of hypertension and insulin resistance in childhood and adolescence." (PMID 40806516, 2025). "At baseline, 86 patients (70.5%) were on oral hypoglycemic agents; 55.6% of 36 insulin users were on statins, 77% of all participants had hypertension, and 51% of obese participants were statin users." (PMID 40785972, 2025).
Hypertension (continued). "There is increasing evidence that gene-physical activity interactions (including being physically active or inactive) have an effect on several health-related outcomes such as blood pressure, hypertension, BMI, and insulin metabolism." (PMID 40951278, 2025). "The 19 variables most closely associated with HF were eGDR, BMI, WC, eGFR, HbA1C, age, DSP, SBP, UA, TC, TG, blood pressure medication, insulin, hypertension, cholesterol-lowering medication, gender, asprin, CVD-PRS, and race." (PMID 40756509, 2025). "We present a 72-year-old Saudi male with T1DM, ischemic heart disease, hypertension, hypothyroidism, and peripheral neuropathy who was transitioned from multiple daily injections to insulin pump therapy." (PMID 41473654, 2025). "In our study, 70.2% of the patients used insulin, and 94.2% had hypertension; these rates were found to be compatible with the literature." (PMID 40710007, 2025). "The percentage of subjects with hypertension and usage of insulin in DR subjects were significantly higher than that of in controls (p < 0.05)." (PMID 41333791, 2025). "Impaired insulin signaling in vascular tissues can lead to endothelial dysfunction, hypertension, and atherosclerosis." (PMID 40336963, 2025). "In a systematic review and meta-analysis, maternal HFD was associated with higher body fat, body weight, leptin, glucose, insulin, triglyceride levels, and hypertension later in life." (PMID 40806516, 2025). "For example, elegant studies evaluating insulin signaling and its role in regulating glucose metabolism have shed light on its broader impact on cardiovascular health, hypertension, atherosclerosis, and other cardiovascular disease risks." (PMID 40403107, 2025). "The decrease in hypertensive diseases is most likely due to improved insulin sensitivity, endothelial function, and systemic inflammation, all of which contribute to the pathophysiology of pregnancy-induced hypertension." (PMID 40430186, 2025). "Vitamin D appears to play a protective role by modulating blood pressure in hypertensive disorders, improving insulin sensitivity in gestational diabetes, and contributing to the regulation of cell proliferation and differentiation in carcinogenesis." (PMID 41041518, 2025). "It is accepted that elevated glucose levels and inappropriate insulin secretion have a synergistic impact on arterial stiffening and play a key role in the early pathophysiology of hypertension and CVD in patients with T1DM and T2DM." (PMID 38255878, 2024). "Reduced insulin signaling, such as that found in insulin-resistant conditions, can lead to significant renal issues, including albuminuria, glomerular disease, and hypertension." (PMID 39457635, 2024). "In contrast, the persistently low BMI group had a lower risk of hypertension and lower levels of SBP, DBP, LDL, and insulin." (PMID 39501285, 2024). "They think that like hypertension or thyroid medication, if they start to take an insulin injection, they have to use it throughout their life, and they think it is required for serious conditions only...you know there are a lot of myths." (PMID 38231562, 2024). "Another animal study that evaluated the effect of increased sympathetic activity on hypertension and insulin sensitivity had similar findings." (PMID 38066299, 2024). "In our cohort, a stepped increase in cardiometabolic comorbidities with CKD severity was observed (hypertension and dyslipidaemia prevalence, glucose, insulin, HOMA-IR, and triglycerides)." (PMID 38638132, 2024). "This was associated with decreased adiponectin and increased FFA levels, hepatic steatosis, and hypertension but normal insulin sensitivity." (PMID 38727299, 2024). "In the multivariable logistic regression, hypertension, peripheral neuropathy, nephropathy, duration of ≥10 years with DM, insulin use and poor adherence to DM medication were found to be statistically significant factors for PDR." (PMID 38728350, 2024).
Hypertension (continued). "It is known that losing weight improves insulin sensitivity and intra- and extra-renal compression, which are significant mechanisms in dysglycemia and hypertension." (PMID 38673521, 2024). "Studies have revealed that GPR75 is involved in insulin secretion and insulin signaling, vascular function and hypertension, neuroprotection, and prostate tumor metastasis." (PMID 39137039, 2024). "Often, prudent dietary patterns such as the Mediterranean diet, plant-based diets, and the Dietary Approaches to Stop Hypertension, or DASH, diet are recommended to aid in weight loss and improve blood glucose regulation and insulin sensitivity." (PMID 37167532, 2024). "This meta-analysis represents the most comprehensive synthesis of prospective cohort studies to date, examining the relationships between fasting insulin levels and the incidence of hypertension, stroke, and coronary heart disease (IHD)." (PMID 39347227, 2024). "Significant variations were identified between patients with and without DPN in terms of sex, age, weight, alcohol consumption, hypertension comorbidity, as well as levels of HbA1c, fasting insulin, HDL-c, creatinine, and VPT (P<0.001)." (PMID 39345878, 2024). "Insulin’s interaction with the vascular, renal, and nervous systems also leads to hypertension, thus demonstrating the interaction between insulin and hypertension in MetS." (PMID 38892574, 2024). "Data were analyzed from 213 patients: 152 (71.4%) were aged above 50 years, 151 (70.9%) were married, 105 (49.3%) had comorbid hypertension, 88 (41.3%) were on glimepiride, 70 (32.9%) were on insulin, and 68 (31.9%) were on ACEIs/ARBs." (PMID 39202585, 2024). "MVMR analysis was also conducted utilizing T2DM, fasting glucose, and fasting insulin levels as exposures, while hypertension, HDL cholesterol, LDL cholesterol, and triglycerides were considered as outcomes, respectively." (PMID 38330008, 2024). "MusS is also associated with decreased risks of age-related weight gain, hypertension (HTN), and MetS and plays a role in improving insulin sensitivity and certain cardiometabolic profiles." (PMID 39189216, 2024). "Considering that hypertension is partially a result of sympathetic overactivation, it is unsurprising that insulin plays a role in modulating sympathetic centers in the brain." (PMID 38337589, 2024). "Patients with CRC displayed a higher likelihood of having hypertension, elevated serum triglyceride levels, and increased insulin levels." (PMID 39113791, 2024). "After adjusting for age, gender, BMI, smoking, duration of T2DM, hypertension, insulin therapy, HbA1c, eGFR, and proteinuria, hyperuricemia remained associated with an increased risk of CKD (adjusted OR 2.10 [1.16–3.76], p = 0.01)." (PMID 38809295, 2024). "This positive correlation was stable in subjects of different genders, ages, races, body mass index, hypertension, and insulin use, but varied in different smoking conditions." (PMID 39850479, 2024). "Type of DM, hemoglobin, glycerol control, duration of DM, hypertension, insulin use, creatinine level, lipoprotein density, hyperlipidemia and proteinuria have been significantly associated with PDR development." (PMID 38728350, 2024). "Among the entire examined diabetic population, 86.3% had a documented history of treated hypertension, 12.6% had a history of smoking, and 57% were treated with insulin." (PMID 38959204, 2024). "Meanwhile, those colchicine users who often use other medications such as anti-hypertension, statins and oral sugar or insulin sometimes forego preventive services such as cancer screening." (PMID 38649928, 2024). "Two hundred three (56.4%) of the participants were receiving non-insulin treatment, and one hundred (27.8%) of them were also diagnosed with hypertension." (PMID 39540008, 2024). "Hypertension, duration of DM ≥10 years, peripheral neuropathy, nephropathy, insulin use and poor adherence to DM medication were significantly associated factors with PDR." (PMID 38728350, 2024).
Hypertension (continued). "Patients in the T3 group had higher glucose, TC, TG, HbA1c, and BMI levels and more frequent history of insulin and oral hypoglycaemic drug use, history of DM, and hypertension than those in the other two groups." (PMID 38218893, 2024). "The activation of GRK2 by some factors such as oxidative stress and insulin impairs the ability of renal D1R to inhibit sodium transport that leads to the development of hypertension." (PMID 38961282, 2024). "In our study, we used eGDR as a validated score based on WC, hypertension, and HbA1c, which was introduced to measure insulin sensitivity in T1D." (PMID 39335526, 2024). "A plant-based diet prevents hypertension and has beneficial effects on blood viscosity, vasodilatation, and reduction of insulin resistance." (PMID 38504199, 2024). "Several preclinical and clinical trials have investigated the effect of RDN in hypertension and concomitantly in the glycemic status of hypertensive patients, in order to determine any beneficial effect of the procedure in glucose and insulin metabolism." (PMID 38066299, 2024). "We conducted subgroup analyses and interaction tests to evaluate the influence of CMI on DKD risk across various diabetic groups, stratified by factors such as age, sex, race, BMI, smoking status, hypertension, and insulin usage." (PMID 39850479, 2024). "We also corroborate that fasting insulin has an indirect effect on essential hypertension mediated by AST." (PMID 38662679, 2024). "Researchers observe a significant relationship between high blood pressure and high insulin levels, probably due to abnormalities in vasodilation and blood flow." (PMID 38441007, 2024). "Fasting plasma glucose and insulin were higher, and insulin sensitivity was lower, in the primary aldosteronism and essential hypertension groups than in controls." (PMID 38406920, 2024). "Participants noted how these medications target blood sugar levels, such as insulin, and a number of comorbidities, such as high blood pressure and cholesterol." (PMID 39237925, 2024). "Model 3 was a multivariable Cox analysis adjusted for age, gender, race, education level, PIR, smoking status, alcohol status, hypertension, use of glucose-lowering drugs or insulin, ALT, HbA1c, and Cr." (PMID 38111710, 2023). "Skinfold-thickness measurements have been demonstrated to have correlation with other health parameters such as abnormal glucose and insulin regulation, while arterial stiffness has been presented as an indicator of hypertension." (PMID 36767026, 2023). "The interaction of insulin–IR and renal absorption of sodium remains an investigational focus for understanding the connection between insulin resistance and arterial hypertension." (PMID 37675359, 2023). "Often pharmacological therapy must be prescribed in order to act on one target: metformin treatment for its insulin sensitizing effect, Orlistat® as a gastric lipase inhibitor or beta-blockers and calcium channel blockers for hypertension." (PMID 36829899, 2023). "Twenty-one percent (21.3%) of participants tested positive for group B Streptococcus (GBS) on screening; 10.4% of participants had hypertension during pregnancy, and 16.5% were diagnosed with gestational diabetes (half of whom were treated with insulin)." (PMID 37065202, 2023). "Patient, known hypertension status, fasting plasma glucose, insulin, uric acid, HDL, low-density lipoprotein (LDL), triglyceride/Tg, HbA1c laboratory values and Tg/HDL ratio were examined." (PMID 38206747, 2023). "Hypertension alters the delivery of insulin and glucose to skeletal cells leading to impaired glucose uptake." (PMID 38465013, 2023). "Overall, children with MAFLD were more likely to have at least one significant cardiometabolic abnormality (hypertension, impaired glucose metabolism, insulin, HOMA-IR or triglycerides or decreased HDL) than did those without MAFLD (82.9% vs 70.6%, p=0.011)." (PMID 37409224, 2023).
Hypertension (continued). "FAM47A and TFE3 were potential risk genes for hypertension, whereas IRS4, an insulin signaling-pathway gene associated with central hypothyroidism, potentially linked with cardiac defects." (PMID 37800145, 2023). "Hypertension can also result from sodium and water metabolism through proximal renal tubular reabsorption, favoured by insulin." (PMID 36677012, 2023). "These included age, sex, stroke severity, smoking status, HR, use of beta blockers and insulin after discharge, levels of total cholesterol and triglyceride, and history of hypertension, atrial fibrillation, and cancer before admission." (PMID 36991469, 2023). "A greater portion of individuals receiving subcutaneous insulin injection and a higher ratio of hypertension were noted in the DN group." (PMID 37008921, 2023). "Participants with a lower serum level of 25(OH)D were more obese and were more prone to have a history of hypertension, along with the therapy of insulin (all p < 0.05)." (PMID 36771345, 2023). "The protein encoded by GNA14 was involved in the regulation of insulin secretion pathway, and the relationship of insulin, insulin sensitivity, and hypertension had been clearly confirmed." (PMID 36869404, 2023). "The rates of insulin use, daily glycemic monitoring, and systemic hypertension treatment were 68.4%, 70.2%, and 70.2%, respectively." (PMID 37430345, 2023). "Those with a higher accumulated hypertension burden were also more likely to receive anti-hypertensive medications, although prescription of oral anti-diabetic medications or insulin and duration of DM > 5 years were less common." (PMID 36658574, 2023). "In sharp contrast, obese females exhibit leptin (and insulin) resistance and are less likely to develop hypertension secondary to sympathoexcitation." (PMID 36769012, 2023). "Genetic susceptibility for hypertension has been proposed to play important role in nearly 50% of insulin resistant individuals to develop hypertension, in the early phase of the disease even after receiving standard antidiabetic treatment." (PMID 37838749, 2023). "The model was adjusted for age, TC, TG, HDL, LDL, FPG, HbA1c, glucagon, C-peptide, insulin, Vit D, current smoking, and hypertension." (PMID 37102159, 2023). "The prevalence of hypertension was higher among the insulin-resistant group, and systolic blood pressure showed significant inverse correlation with insulin sensitivity." (PMID 37274075, 2023). "We corrected some confounding factors (DN, DR, DPN, DF, insulin use history, biguanide use history, thiazolidines use history, antihypertensive drug use history, hypertension history, A/G, ACR, TC, TG, HDL, LDL, eGFR, P, Ca, HbA1c, serum C-peptide)." (PMID 38144561, 2023). "MetS refers to a collection of many variables, which include hypertension, dyslipidemia, cellular resistance to insulin, obesity, and glucose intolerance." (PMID 38288203, 2023). "Around half of hypertension patients are insulin resistant, and this disturbance in insulin metabolism has been increasingly linked to the development of hypertension and related cardiovascular diseases (CVD)." (PMID 37904206, 2023). "High Lp(a) levels were an independent predictor of adverse outcomes along with hypertension, previous heart failure and coronary artery bypass graft, the prescription of insulin at discharge from the index event, and older age." (PMID 36769608, 2023). "According to a study from the KSA, female sex, hypertension, insulin treatment, a body mass index (BMI) of more than 30 kg/m2, and nephropathy all raise the incidence of UTIs in diabetic patients." (PMID 36981518, 2023). "Indeed, vasodilator nitric oxide (NO) is stimulated by insulin, and in a healthy state, the release of insulin after eating causes the skeletal-muscle vasculature to dilate, but in conditions of insulin resistance, NO is decreased, and this may cause hypertension." (PMID 37645243, 2023).